APOE (apolipoprotein E)
Diseases named in the same sentence as APOE in open-access papers (continued):
Sharing a sentence is not in itself a finding about the gene and the disease.
dementia (continued). "The two diagnostic groups (CNI and MCI) were relatively similar in sociodemographic, medical and emotional conditions at baseline, including family history of dementia, except that MCI persons were older and more likely to be APOE ε4 allele carriers." (PMID 36900708, 2023). "Of the APOE e4 carries with both low vitamin D and grip strength, 6.4% (95% CI 5.9–7.0%) incident dementia compared to 2.4% (95% CI 2.1–2.7%) of APOE e4 carries with both high vitamin D and grip strength." (PMID 37246226, 2023). "We previously demonstrated that MCI conversion to the dementia stage can be predicted by a lower plasma Aβ1-42 and Aβ1-42/Aβ1-40 ratio, independently of age, sex, education level, and APOE E4." (PMID 38139190, 2023). "The first assumption proposed previously is that the cognition function of APOE ε2 carriers is higher than APOE ε4 carriers in non-dementia older, especially in the memory cognitive domain, which was verified." (PMID 37636817, 2023). "The combination of ideal vitamin D and handgrip strength seemed to counteract the adverse effects of APOE e4 genotype on dementia by almost 50%." (PMID 37246226, 2023). "There were significant additive interactions between lower vitamin D/grip strength and APOE e4 genotype on dementia among women and men." (PMID 37246226, 2023). "Participants who developed dementia were more likely to be older, female, Black, or APOE-ε4 carriers." (PMID 36622673, 2023). "Of the 502,536 samples, in this study we included the incident dementia cases and controls, while excluding the prevalent cases and individuals with the APOE ε2/APOE ε4 genotype." (PMID 37467176, 2023). "Using a similar method to that of Klunk and colleagues, Pardo and Lee also found that peak amyloid deposition localized principally to the putamen compared with other brain areas in non-dementia APOE ε4 homozygotes." (PMID 37636817, 2023). "A third limitation is the role of APOE status as a risk factor or modifier of the relationship between SCD and dementia exposure." (PMID 37497342, 2023). "Participants with dementia were more likely to be older; male; previous or current smokers; APOE ε4 carriers; with a lower education level and alcohol intake frequency; and had a higher prevalence of CVD, hypertension and diabetes." (PMID 37198574, 2023). "Adjusted for APOE-ɛ4, individuals with PRS corresponding to the fourth quartile had an increased risk of dementia compared to the first quartile (OR 1.85; p-value 0.002)." (PMID 37834213, 2023). "Furthermore, a previous study showed that single nucleotide polymorphisms (SNPs) rs429358 and rs7412 of the APOE gene are associated with ischemic cerebral infarction, which is essential given the contribution of cerebrovascular diseases in the pathophysiology of many dementia cases." (PMID 36046159, 2022). "The current study examined the underlying resting state functional connectivity (RSFC) associated with impaired non-standard visuomotor performance, as well as the impacts of dementia family history, sex, and APOE status." (PMID 36533177, 2022). "Similar to findings from HICs, non‐modifiable risk factors for progression to dementia from MCI included age62, 63, 64, 65 and APOE ε4 allele status." (PMID 35310524, 2022). "While when dementia cases occurred from 10 years onward, the associations for ACD only persisted in models unadjusted or adjusted for age, sex, ApoE-ε4, and education, and the associations for VD were consistently robust in all models." (PMID 36100869, 2022). "After adjustment for socio-demographic characteristics, lifestyle, APOE-ε4, cardiovascular factors, and depressive status, EDS had a higher risk of all-cause dementia (HR = 1.21; 95%CI = [1.01–1.46]) and DVC (HR = 1.58; 95%CI = [1.07–2.32]) but not AD." (PMID 35057850, 2022).
dementia (continued). "To our knowledge, we provide evidence for the first time of an APOE genotype-dependent difference in HDL functional capacity, size, and dementia and also an association between HDL functional capacity, size, and cognitive function." (PMID 35884800, 2022). "In modelling combining all biomarkers with baseline age, gender and MDS-UPDRS 3, only APOE ε4 status (HR 2.75, 95% CI 1.44 to 5.24, p=0.002) and Nfl (HR 2.09, 95% CI 1.16 to 3.76, p=0.014) continued to significantly predict progression to dementia." (PMID 35577512, 2022). "We enrolled 600 dementia cases and 6000 matched non-dementia controls, with identified ApoE genotype (ε4/ε4, ε4/ε3, and ε3/ε3)." (PMID 36578446, 2022). "We then calculated the relationship of three AD risk factors, namely Apolipoprotein-E ɛ4 (APOE4) genotype, family history of dementia (FH), and central obesity (Waist-Hip-Ratio [WHR]), on graph theoretical measures and hubs." (PMID 34030485, 2022). "This is a cross-sectional study with a total of 520 patients undergoing dementia investigation, including an MRI brain scan and APOE genotyping in all patients enrolled, and cerebrospinal fluid (CSF) analysis for routine AD biomarkers in 399 patients." (PMID 35912087, 2022). "The risk factors investigated were Apolipoprotein-E ɛ4 (APOE4), family history of dementia (FH), and central obesity as assessed with the Waist-Hip-Ratio (WHR)." (PMID 34030485, 2022). "The objectives of this study was to estimate the incidence of dementia in a population of Italian elders and evaluate the role of walking speed, comorbidity and ApoE-ɛ4 as well as various sociodemographic factors on the new onset of dementia." (PMID 35888143, 2022). "Morin post-treatment confers neuroprotection in a novel rat model of mild repetitive traumatic brain injury by targeting dementia markers, APOE, autophagy and Wnt/β-catenin signaling pathway." (PMID 36187470, 2022). "Its secondary aim was to ascertain the predictive roles of walking speed, comorbidities, ApoE-ɛ4 and sociodemographic factors, specifically year of birth, education and gender on the onset of dementia." (PMID 35888143, 2022). "Variables, such as age, education, the scores of visuospatial and memory domains, the sum of boxes of the Clinical Dementia Rating scale, Mini-Mental State Examination, and APOE genotype were important features for creating the algorithm." (PMID 35992586, 2022). "The results of this study suggest that there is an interplay between dietary patterns and APOE ε4 status in relation to incident dementia." (PMID 34632537, 2022). "The main interest of this study was to investigate the grey and white matter neural anatomy underlying impaired visuomotor performance, and to explore the effects of family history of dementia, APOE genotype, and sex." (PMID 36711200, 2022). "CSF AD status, APOE ε4 carrier status, sex, clinical dementia rating (CDR), and Mini Mental State Examination test (MMSE) scores were significantly different between NPS positive and NPS negative groups." (PMID 35326481, 2022). "As far as non-invasive markers of dementia are concerned, we only have age and Apolipoprotein-E (Apo-E) gene, which can be considered as clinically relevant." (PMID 35621297, 2022). "Interactions were observed between adherence to the dietary patterns and APOE ε4 status in relation to incident dementia (interaction p value threshold of < 0.1)." (PMID 34632537, 2022). "A secondary analysis of a randomized controlled trial of nilvadipine among individuals with dementia found a significant interaction between APOE ε4 status and AC burden score on the CDR (one of three cognitive outcomes in the study)." (PMID 36506252, 2022). "Another possible target of ApoE is α-synuclein, a protein involved in dementia with Lewy bodies, including PD." (PMID 35327638, 2022).
dementia (continued). "Use in clinical practice will necessitate more precise estimates of when patients develop dementia and it will be important to establish the success of combining GBA and APOE mutations with other predictors." (PMID 35106798, 2022). "Higher amyloid levels and APOE ɛ4 most strongly increased the hazard of incident dementia in women and men." (PMID 35310829, 2022). "The current study investigated the relationship between grey and white matter changes and non-standard visuomotor performance, as well as the effects of APOE status, family history of dementia, and sex on these brain-behavior relationships." (PMID 36711200, 2022). "The gene encoding apolipoprotein E (APOE), located on chromosome 19, has been consistently linked to LOAD, and the ε4 allele is considered the most significant risk factor for this dementia." (PMID 39081475, 2022). "The results of this study suggest that there is an interplay between APOE ε4 status and adherence to dietary patterns in relation to incident dementia." (PMID 34632537, 2022). "Per standard deviation (SD) increase in z-GRS including APOE, the odds ratio (OR) for dementia was 1.73 (95%CI 1.69–1.77)." (PMID 36477264, 2022). "Given that APOE ε4 and BIN1 are considered risk factors for AD and that previous studies have shown an association between respiratory diseases such as COPD and dementia, one would expect that carriers of these risk variants would be more prone to RESP." (PMID 39081475, 2022). "Collectively, the APOE3-Jacksonville and APOE4-R251G protective variants offer new clues as to how apoE C-terminal domain impacts AD and related dementias and how knowledge learned from them can guide new apoE-targeting strategies." (PMID 35922805, 2022). "In the prospective Honolulu-Aging study, the relation between dementia having serum levels of apolipoprotein A-I (Apo-AI) alone and combined levels with Apolipoprotein E (Apo-E) genotype were examined." (PMID 35621297, 2022). "Taken together, self-reported sleep problems among people with dementia are characterized by very short or long sleep duration, lower sleep efficiency, and EDS, especially among young-old adults and APOE ε4 allele carriers." (PMID 34979998, 2022). "Visuomotor impairments have been demonstrated in preclinical AD in individuals with a positive family history of dementia and APOE e4 carriers." (PMID 36711200, 2022). "The fact that hazard and remaining lifetime risk of incident dementia varied dramatically by the subgroups examined suggests that it might be useful to take a more granular approach to inclusion and stratification based on combinations of sex, APOE ɛ4 and amyloid level." (PMID 35310829, 2022). "In this prospective observational study conducted within the Framingham Offspring Cohort (1490 dementia-free participants aged ≥65 years old), we examined the association of RBC DHA with incident AD, testing for an interaction with APOE-ε4 carriership." (PMID 35745137, 2022). "We found interactions between dietary patterns and APOE ε4 status in relation to incident dementia among 70-year-olds in a population-based sample followed on average for 13 years." (PMID 34632537, 2022). "In this study, we explored the role of the ApoE-ɛ4 carrier status and sex in modulating fatty acid metabolism and related pathways in early CD, before the appearance of dementia symptoms." (PMID 34980257, 2022). "Several factors, including age, sex, neuropsychological test results, and apolipoprotein E (APOE) genotype were found to affect the rate of conversion to dementia." (PMID 35992586, 2022). "Using a cohort of postmortem AD brain samples, we examined CA in cognitively normal and dementia patients across Braak stages with varying APOE status." (PMID 35941704, 2022). "This is one of few studies that have investigated interactions between different dietary patterns and both APOE ε4 status and non-APOE ε4 PRSs in relation to dementia." (PMID 34632537, 2022).
dementia (continued). "The results of the present study confirm the strong influence of ApoE-ɛ4 status on dementia onset that has previously been demonstrated by others." (PMID 35888143, 2022). "After 12 months of follow-up, compared with the nondementia group, the number of WMV, WMH, Fazekas scores, and APOE-ε4 gene carriers in the dementia group was significantly increased." (PMID 35317127, 2022). "Apolipoprotein E (Apo-E) is a primary cholesterol carrier involved in lipid transport, and APOE ε4 alleles are the main genetic risk factors for AD and dementia due to their reduced capacity for Aβ transport." (PMID 36045363, 2022). "Several studies and meta-analyses have demonstrated an over-representation of APOE ε4 carriers amongst individuals with PD cognitive impairment and dementia, although others have been equivocal or provided only modest evidence." (PMID 36371506, 2022). "The results of the present study confirm previous literature evidence on the influence of certain factors, such as age walking speed, education and ApoE-ɛ4 status on the incidence of dementia." (PMID 35888143, 2022). "The percentages of APOE ε4, Mini‐Mental State Examination, and Clinical Dementia Rating scores were significantly different between aMCI patients and controls, AD patients and controls, VaD patients and controls, as well as AD and aMCI patients (all p < 0.05)." (PMID 35470961, 2022). "The APOE ε4 genotype was also found to play an important role in conversion to dementia, which was again consistent with previous studies." (PMID 35992586, 2022). "There is a probable selection bias in our cohort towards individuals with increased heredity for dementia and a higher proportion of APOE ε4 carriers compared to the general population, also among the controls, as a consequence of our recruitment strategy." (PMID 32955960, 2021). "Our findings further characterize the role of APOE in dementia onset and diagnosis as well as the potential influences of sex or race on diagnosis." (PMID 34744974, 2021). "Prediction ability of AD, VD, MD, and all-cause dementia by the PRS and APOE was assessed by multiple logistic regression and receiver operating characteristic curve analyses." (PMID 32404947, 2021). "While it seems likely that APOE ε4 mediates dementia through an Aβ-dependent pathway, previous studies have also reported an effect of APOE ε4 on cognitive outcome and severity of cortical LB pathology in patients with low concomitant AD-pathology." (PMID 33613437, 2021). "Participants who were dementia-free at death were more likely to be male (46% compared with 59% of those with a dementia diagnosis) and were less likely to be an APOE ε4 carrier than were those who experienced a dementia diagnosis." (PMID 34744974, 2021). "Common genetic variation of the Apolipoprotein E (APOE) and micro-tubule associated protein tau (MAPT) loci have been linked to cognitive decline and dementia in Parkinson's disease, although studies have yielded mixed results." (PMID 33613437, 2021). "Common genetic variation of the apolipoprotein E (APOE) ε4 allele and microtubule-associated protein tau (MAPT) H1-haplotype have been linked to earlier development of dementia in patients with PD." (PMID 34833115, 2021). "In particular, ADAS-viewer allows the separation of two groups based on clinical features such as sex, Braak Score, ethnicity, education level, dementia status, ApoE status, disease status, and more." (PMID 33741983, 2021). "The Rotterdam study reported an effect of AD‐PRS (including 23 SNPs) on dementia, with the strongest effects in APOE ɛ4 carriers." (PMID 33532541, 2021). "It is unclear why APOE ε4 has remained highly prevalent in the population over the course of evolution despite its deleterious effects on dementia and cardiovascular health." (PMID 33397450, 2021).
dementia (continued). "Meanwhile, the relation of many risk factors, such as the apolipoprotein E (ApoE) genotype, and lifestyle factors for predicting progression from mild cognitive impairment (MCI) to dementia has been reported in many cohort studies." (PMID 35002683, 2021). "We performed the following analysis on the dataset matched on statin PS, thus including as covariates sex, APOE genotype, AD, dementia diagnoses, and their interactions with statin treatment." (PMID 33969178, 2021). "In this study, we leveraged PET imaging data from the Translational Biomarkers in Aging and Dementia cohort at McGill University Research Centre for Studies in Aging to elucidate the APOE-by-sex interactive effect on tau burden." (PMID 34189460, 2021). "We looked for differences in age, gender, education, ApoE-e4 carrier status and obesity, and then investigated the influence of the observed trajectories on the incidence of dementia." (PMID 33594647, 2021). "The unadjusted model indicated that Apathy class was the best predictor, while once adjusted (including APOE-Ɛ4 and the rest of variables), Irritability emerged as the most relevant neuropsychiatric condition when predicting conversion to dementia." (PMID 33742011, 2021). "Regarding APOE genotype, typical of such samples, 21.1% of CN, 64.3% of aMCI, and 70.8% dementia participants carried at least one copy of APOE ε4." (PMID 33402201, 2021). "Another recent Meta-Analysis based on 27 studies with 3136 dementia and 3103 healthy controls reported that circulating cholesterol was significantly increased in APOE ε4 carriers in mixed populations." (PMID 34828374, 2021). "Among APOE ɛ4 non‐carriers, the 39‐SNPs AD‐PRS remained associated with incident dementia after removal of rs876461, rs117618017, and rs4844610 (for all analyses: P = 2 × 10–4)." (PMID 33532541, 2021). "The findings indicate that when taken in conjunction with the APOE genotype, TOMM40 ‘523’ allele length is a significant independent determinant and marker for the trajectory of cognitive decline and risk of dementia in PD." (PMID 34234128, 2021). "In conclusion, our study adds to the growing evidence supporting the role for not only APOE ε4 but also the MAPT H1 haplotype in development of dementia in PD." (PMID 33613437, 2021). "Cumulative incidence for all‐cause dementia and cognitive decline was calculated with mortality as a competing event, stratified by APOE genotypes and tertiles of a PRS based on 23 common non‐APOE variants." (PMID 34041846, 2021). "A previous study by our group revealed that APOE ε4 predicted more rapid hippocampal and cortical atrophy in dementia with AD21." (PMID 33603015, 2021). "Median age (years) of dementia diagnosis or dementia-free death by APOE ε4 status in the ARIC cohort (N = 13,782)a." (PMID 34744974, 2021). "Greater CSVD severity on MRI, CAA hemorrhage etiology and APOE variant ε4 all independently predicted expression of Profile III (late depression and dementia risk)." (PMID 34893031, 2021). "The APOE has been identified as a biomarker for prognosis of mild cognitive impairment and AD and for diagnosis of depressive disorder and dementia and used as a biomarker for measuring the efficacy of testosterone in treating AD and mild cognitive impairment." (PMID 34470669, 2021). "We examined the effect of AD‐PRSs and APOE genotype on incident dementia, in a large population‐based study of individuals aged 70 to 111 years." (PMID 33532541, 2021). "Taken together, the weight of evidence favors an effect of APOE on cognitive decline and dementia in PD, further supported by our results." (PMID 33613437, 2021). "Few studies have measured the effect of Apolipoprotein E (APOE) genotypes and polygenic risk scores (PRS) on incident dementia and cognitive decline in healthy older people." (PMID 34041846, 2021).